TGFBR1 (transforming growth factor beta receptor 1)
Description:
Transmembrane serine/threonine kinase forming with the TGF-beta type II serine/threonine kinase receptor, TGFBR2, the non-promiscuous receptor for the TGF-beta cytokines TGFB1, TGFB2 and TGFB3. Transduces the TGFB1, TGFB2 and TGFB3 signal from the cell surface to the cytoplasm and is thus regulating a plethora of physiological and pathological processes including cell cycle arrest in epithelial and hematopoietic cells, control of mesenchymal cell proliferation and differentiation, wound healing, extracellular matrix production, immunosuppression and carcinogenesis. The formation of the receptor complex composed of 2 TGFBR1 and 2 TGFBR2 molecules symmetrically bound to the cytokine dimer results in the phosphorylation and the activation of TGFBR1 by the constitutively active TGFBR2. Activated TGFBR1 phosphorylates SMAD2 which dissociates from the receptor and interacts with SMAD4. The SMAD2-SMAD4 complex is subsequently translocated to the nucleus where it modulates the transcription of the TGF-beta-regulated genes. This constitutes the canonical SMAD-dependent TGF-beta signaling cascade. Also involved in non-canonical, SMAD-independent TGF-beta signaling pathways. For instance, TGFBR1 induces TRAF6 autoubiquitination which in turn results in MAP3K7 ubiquitination and activation to trigger apoptosis. Also regulates epithelial to mesenchymal transition through a SMAD-independent signaling pathway through PARD6A phosphorylation and activation.
Synonyms: TGFR-1; ALK-5; ALK5; SKR4; TbetaR-I; ACVRLK4; TBRI; TBR-i; AAT5; ESS1; LDS1; LDS1A; LDS2A; MSSE
Tractability: Small molecule: a drug acting on it is in phase 2 or 3 trials; a structure with a bound ligand is known; a high-quality ligand is known; it has a high-quality binding pocket; it belongs to a druggable protein family. Antibody: UniProt places it where antibodies can reach, with high confidence; its Gene Ontology location is reachable by antibodies, with high confidence; UniProt predicts a signal peptide or a membrane-spanning region; the Human Protein Atlas places it where antibodies can reach. PROTAC: it is named in the literature on targeted protein degradation; UniProt records ubiquitination sites on it; ubiquitination databases record sites on it; its protein half-life has been measured; a small molecule that binds it is known.
Target class: Enzyme; TKL protein kinase group; TKL protein kinase STKR family; TKL protein kinase STKR Type 1 subfamily; Protein Kinase; Kinase
Chemical probes: BI-4659 (high quality), BIBF0775, GW693481X, GW788388 (high quality), TP-008 (high quality)
Gene: Protein-coding gene on chromosome 9 (99,104,038 to 99,154,192, forward strand). Ensembl gene ENSG00000106799.
Subcellular location: Cell membrane; Cell junction, tight junction; Cell surface; Membrane raft
Subcellular location (Human Protein Atlas): Plasma membrane; Primary cilium; Primary cilium tip
Pathways (Reactome):
Disease: SMAD2/3 Phosphorylation Motif Mutants in Cancer; TGFBR1 KD Mutants in Cancer; TGFBR1 LBD Mutants in Cancer; TGFBR2 Kinase Domain Mutants in Cancer
Signal Transduction: Downregulation of TGF-beta receptor signaling; TGF-beta receptor signaling activates SMADs; TGF-beta receptor signaling in EMT (epithelial to mesenchymal transition); TGFBR3 regulates TGF-beta signaling
Metabolism of proteins: UCH proteinases; Ub-specific processing proteases
Gene Ontology:
Molecular function: ATP binding; growth factor binding; I-SMAD binding; protein binding; protein kinase activity; protein serine/threonine kinase activity; SMAD binding; transforming growth factor beta binding; transforming growth factor beta receptor activity; transforming growth factor beta receptor activity, type I; transmembrane receptor protein serine/threonine kinase activity; type II transforming growth factor beta receptor binding; ubiquitin protein ligase binding; activin binding; activin receptor activity, type I; signaling receptor binding
Biological process: cell motility; cellular response to transforming growth factor beta stimulus; epithelial to mesenchymal transition; myofibroblast differentiation; negative regulation of cell migration; negative regulation of extrinsic apoptotic signaling pathway; peptidyl-serine phosphorylation; positive regulation of apoptotic signaling pathway; positive regulation of cell growth; positive regulation of cell migration; positive regulation of cell population proliferation; positive regulation of DNA-templated transcription; positive regulation of extracellular matrix assembly; positive regulation of gene expression; positive regulation of mesenchymal stem cell proliferation; positive regulation of phosphatidylinositol 3-kinase/protein kinase B signal transduction; positive regulation of SMAD protein signal transduction; positive regulation of vasculature development; regulation of DNA-templated transcription; regulation of protein ubiquitination; response to cholesterol; signal transduction; transforming growth factor beta receptor signaling pathway; trophoblast cell migration; activin receptor signaling pathway; and 45 more
Cellular component: bicellular tight junction; cell surface; endosome; membrane raft; nucleus; plasma membrane; receptor complex; transforming growth factor beta ligand-receptor complex; activin receptor complex; membrane
Genetic constraint (gnomAD): Loss-of-function variants: 20 observed, 57.15 expected, observed/expected ratio (o/e) 0.35, 90% interval 0.25 to 0.51. The upper end of that interval is the gene's LOEUF score, 0.51, which puts it in group 2 of 6, group 1 being the genes least tolerant of losing a copy. Missense variants: 383 observed, 635.25 expected, observed/expected ratio (o/e) 0.6, 90% interval 0.55 to 0.66. Synonymous variants: 220 observed, 217.78 expected, observed/expected ratio (o/e) 1.01, 90% interval 0.9 to 1.13.
Gene-disease validity (ClinGen):
ClinGen rates the evidence that TGFBR1 causes each of these diseases.
Loeys-Dietz syndrome (autosomal dominant): Definitive. Loeys-Dietz syndrome is a rare genetic connective tissue disorder characterized by a broad spectrum of craniofacial, vascular and skeletal manifestations with four genetic subtypes described forming a clinical continuum.
multiple self-healing squamous epithelioma (autosomal dominant): Definitive.
Homologues: Orthologues: macaque TGFBR1 (99% identical), dog TGFBR1 (98% identical), mouse Tgfbr1 (96% identical), rat Tgfbr1 (96% identical), guinea pig TGFBR1 (96% identical), chimpanzee TGFBR1 (95% identical), rabbit TGFBR1 (94% identical), pig TGFBR1 (91% identical), tropical clawed frog tgfbr1 (83% identical), zebrafish tgfbr1b (81% identical), zebrafish tgfbr1a (77% identical). Paralogues in human: ACVR1B (69% identical), ACVR1C (66% identical), BMPR1B (51% identical), BMPR1A (50% identical), ACVR1 (48% identical), ACVRL1 (46% identical), ACVR2A (31% identical), TGFBR2 (31% identical), ACVR2B (29% identical), BMPR2 (27% identical), AMHR2 (26% identical).
Diseases named in the same sentence as TGFBR1 in open-access papers:
TGFBR1 is named in the same sentence as 333 diseases in open-access papers, as found by Europe PMC text mining. Sharing a sentence is not in itself a finding about the gene and the disease. The quoted sentences say what the papers report.
breast carcinoma (92 papers, 2004 to 2025). "In the Kaklamani 200526 study that included >80% Caucasians from New York, NY, TGFBR1*6A association with breast cancer risk was significant under both dominant (OR 1.50, 95% CI 1.07-2.11) and additive (OR 1.46, 95% CI 1.04-2.06) models." (PMID 35853889, 2022). "Five of the studies found evidence that supports the association between TGFBR1*6A and breast cancer risk." (PMID 35853889, 2022). "Here, the authors find that short-term TGFBR1 inhibition prevents tumour formation in rat breast cancer models and identify a TGFBR1 inhibition-responsive sub-population of mammary epithelial cells, which is associated with human breast cancer risk." (PMID 36476730, 2022). "Overall, most meta-analyses published to date show an association between TGFBR1*6A and breast cancer risk." (PMID 35853889, 2022). "Despite TGFBR1*6A and TGFBR1 physicochemical similarities, TGFBR1*6A is intriguingly associated with breast cancer risk, and promotion of cell growth, migration, and invasion." (PMID 35853889, 2022). "Three of the most recent meta-analyses that investigated up to 17 case/control studies (14,068 subjects) found an association between TGFBR1*6A and breast cancer risk." (PMID 35853889, 2022). "Genetic association studies have identified TGFBR1*6A as a high frequency, low penetrance breast cancer susceptibility allele in breast cancer patients of varied ethnic backgrounds and geographical locations." (PMID 35853889, 2022). "Nineteen case-control studies that included 14,837 participants (6787 cases/8,050 controls) have investigated the association of TGFBR1*6A with breast cancer risk." (PMID 35853889, 2022). "Published case-control studies examining the association of TGFBR1*6A with breast cancer risk among individuals from different geographical locations and ethnicities show both significant and non-significant risk associations." (PMID 35853889, 2022). "The TGFBR1*6A allele has been associated with increased breast cancer risk in women, OR 1.15 (95% CI 1.01–1.31)." (PMID 35853889, 2022). "Among the diseases, the top five diseases with a high score of TGFBR1-neoplasm association were cancer, multiple keratoacanthomata, Ferguson-Smith type carcinoma, glioma, and breast carcinoma." (PMID 32582282, 2020). "In summary, this meta-analysis provided evidence that the TGFBR1*9A/6A polymorphism is associated with overall cancer susceptibility and seem to be more susceptible to ovarian and breast cancer." (PMID 22905183, 2012). "Transforming growth factor β1 (TGFB1) T29C and TGF β receptor type 1 (TGFBR1) 6A/9A polymorphisms have been implicated in the modulation of risk for breast cancer in Caucasian women." (PMID 21829601, 2011). "TGFBR1*6A mutation can lead to the development of breast cancer, ovarian cancer, and renal cell carcinoma amongst others." (PMID 20429896, 2010). "The Int7G24A variant of transforming growth factor-beta receptor type I (TGFBR1) has been shown to increase the risk for kidney, ovarian, bladder, lung and breast cancers." (PMID 19930569, 2009). "In the high-risk familial breast cancer group, we found the frequency of both TGFBR1 variants to be lower than among the controls." (PMID 17848956, 2007). "The TGFBR1*6A allelic frequency was, however, higher in low-risk familial breast cancer (0.138), compared to controls (0.106; P=0.04)." (PMID 17848956, 2007). "Two common variants in transforming growth factor-β receptor 1 (TGFBR1), TGFBR1*6A and Int7G24A, A allele, have been shown to act as low-penetrance tumour susceptibility alleles in several common cancers, including breast cancer." (PMID 17848956, 2007). "The TGFBR1*6A variant was found to be associated with an increased risk for breast cancer in the low-risk familial breast cancer group." (PMID 17848956, 2007).
breast carcinoma (continued). "We therefore chose to analyse the genotype distribution and allelic frequency of TGFBR1*6A in two cohorts of patients with a well-defined family history and classified the patients in high- and low-risk family history and sporadic breast cancer." (PMID 17848956, 2007). "TGFBR1*6A carrier status was further associated with a high-grade sporadic breast cancer (odds ratio: 2.27; 95% confidence interval: 1.01–5.11; P=0.049)." (PMID 17848956, 2007). "However, they did establish a strong correlation between an inherited variant in TGFBR1 and patients facing advanced stages of breast cancer." (PMID 39594781, 2024). "This review details our current clinical and pre-clinical knowledge on TGFBR1*6A as a high frequency, low penetrance tumor susceptibility allele, and provides further rationale to assess its role as a modifier gene for breast cancer predisposition and tumor progression." (PMID 35853889, 2022). "However, subgroup analyses showed that TGFBR1*6A was associated with increased risk among low-risk familial breast cancer patients with one first- or second-degree breast cancer relative (OR 1.3, 95% CI 1.0–1.9)." (PMID 35853889, 2022). "In all, eight meta-analyses have studied the association of TGFBR1*6A with breast cancer risk." (PMID 35853889, 2022). "In summary, it appears that TGFBR1*6A is a common breast cancer susceptibility allele in diverse ethnic backgrounds and its influence may vary by ancestry, geographical location, and other risk modifying factors." (PMID 35853889, 2022). "This review discusses current findings on the genetic, functional, and mechanistic associations between TGFBR1*6A and breast cancer risk and proposes future directions as it relates to genetic association studies and mechanisms of action for tumor growth, metastasis, and immune suppression." (PMID 35853889, 2022). "Further investigations into the risk associated with individual TGFBR1*6A genotypes as well as their correlation with breast cancer subtypes, disease progression (tumor grade), metastasis, and survival are needed to clarify the population-specific susceptibilities of TGFBR1*6A carriers." (PMID 35853889, 2022). "Notably, a variant of TGFBR1 (TGFBR1*6A) has been found to enhance the migration and invasion of breast cancer cells." (PMID 25938468, 2015). "In summary, the present study on TGFB1 T29C and TGFBR1 6A/9A polymorphisms in relation to breast cancer risk has revealed important differences between the genotypes and allele frequencies in premenopausal Maharashtrian women, compared to Parsi and White women." (PMID 21829601, 2011). "However, a recent meta analysis supported the increased breast cancer risk in women positive for the TGFBR1*6A allele." (PMID 21829601, 2011). "TGFBR1 6A/9A polymorphism and risk for breast cancer in Maharashtrian and Parsi women." (PMID 21829601, 2011). "Similar computations for TGFBR1*6A allele indicate that for a fifteen percent increment in the risk for breast cancer due to presence of this allele, nearly twenty thousand patients and controls would be needed whereas, to determine its effect recessively, over a million subjects would be needed." (PMID 21829601, 2011). "The role of TGFBR1*6A variant in breast cancer is controversial." (PMID 17848956, 2007). "Thus, the effects of higher frequency of TGFB1*29C allele, alone and in association with the lower frequency of TGFBR1*6A allele, may have implications for the lower incidence of breast cancer in this population." (PMID 21829601, 2011). "In the present study, we evaluated the frequencies of TGFBR1 9A/6A and Int7G24A variants in two breast cancer cohorts with a defined family history and controls from Stockholm, Sweden and also examined whether these variants were associated with tumour presentation and prognosis." (PMID 17848956, 2007).
breast carcinoma (continued). "Although the TGFBR1*6A polymorphism has been associated with breast cancer risk in a meta-analysis (with a total of 1,420 cases and 3,451 controls), we did not see any evidence of a relationship between this microsatellite and breast cancer in our large nested case-control study." (PMID 17848193, 2007). "Our results indicate that the TGFBR1*6A variant might confer an increased risk of breast cancer in families classified as having a low-risk familial history, even though there was only statistical significance on the allelic level, and not in the genotype distribution." (PMID 17848956, 2007). "We evaluated the TGFBR1 9A/6A and Int7G24A variant frequencies in two breast cancer cohorts; a population-based cohort of breast cancer with defined family history (n=459) and in breast cancer patients from a familial cancer clinic (n=340) and in 856 controls from the Stockholm region." (PMID 17848956, 2007). "Data analysis clearly suggested lower expression of TGFBR1 in later staging of breast cancer with poor progression in TNBC." (PMID 37333824, 2023). "Targeting the elevated expression of TGFBR1 with the inhibitor, EW-7195 can prevent metastasis of breast cancer cells to lungs by supressing Smad signalling." (PMID 37333824, 2023). "The TGFBR1*6A allelic frequency also ranged from 6.1 to 12.8% among breast cancer patients from northern and southwestern Europe, including samples from the UK36, Spain32, Sweden37, Finland38, Poland38,39, and Ireland40." (PMID 35853889, 2022). "Functionally, TGFBR1*6A promotes breast cancer cell proliferation, migration, and invasion through the regulation of the ERK pathway and Rho-GTP activation." (PMID 35853889, 2022). "We found that the expression level of TGFBR1 was mainly correlated with the level of macrophage infiltration in different breast cancer subtypes." (PMID 34485309, 2021). "Through database analysis, we found that the expression levels of TGFB1 and TGFBR1 in breast cancer are correlated with the infiltration levels of multiple immune cells." (PMID 34485309, 2021). "TGF-β signaling in breast cancer cells was modulated by expression of kinase-inactive TGFBR1-K232R (dnTGFBR1) or constitutive-active TGFBR1-T204D (caTGFBR1) receptor mutants." (PMID 29921235, 2018). "Studies have also shown that repression of TGFBR1 inhibited cell proliferation of lung cancer and cell migration and invasion of breast cancer." (PMID 29371929, 2017). "So far, the direct validated targets of this miRNA include stem cell self-renewal regulator SOX2 in breast cancer, TGFBR1 and FGF9 in hepatocellular carcinoma, SOX9 and ALDH1 in ductal carcinoma in situ and IGF1R in lung cancer." (PMID 26882564, 2016). "In breast cancer patients, TGFB1 T29C (L10P; rs1800470) and TGFBR1 6A/9A remain the two most extensively studied polymorphisms." (PMID 21829601, 2011). "Our finding of decreased metastasis in osteosarcoma cases with TGFBR1*6A contrasts with the result with in breast cancer cells." (PMID 20429896, 2010). "BMP2, BMP4, GDF15 and TGFBR1 were significantly correlated with T stage of breast cancer." (PMID 37333824, 2023). "Additionally, lower expression of TGFBR1 was observed in the locally advanced tumours (T3 and T4) in TNBC breast cancers, which was associated with poor OS in TNBC." (PMID 37333824, 2023). "Notably, the relative expression of TGFBR1 was negatively correlated with the cumulative survival of breast cancer (BRCA) and pancreatic cancer patients." (PMID 37328484, 2023). "Importantly, TGFBR1*6A switched TGF-β anti-proliferative effects into growth stimulatory effects in the MCF-7 breast cancer cells." (PMID 35853889, 2022). "The study noted that TGFBR1*6A allelic frequency among Caucasians from the UK does not differ by age of onset (<40 years), bilateral breast cancer, family history, and germline mutations of BRCA1 and BRCA236." (PMID 35853889, 2022).